TNF (tumor necrosis factor)
Diseases named in the same sentence as TNF in open-access papers (continued):
Sharing a sentence is not in itself a finding about the gene and the disease.
Arthritis (continued). "Because CD69 potentially plays a role in the pathogenesis of arthritis, our findings suggest that neutrophils are among the targets of anti-TNF-α activity in RA and may provide an insight into a new and interesting mechanism of action of anti-TNF-α mAbs in the control of inflammatory arthritis." (PMID 15743471, 2005). "TNFα is recognised as a potentially powerful immune mediator and multifunctional cytokine that regulates the central aspects of host defence responses and plays a major role in the pathogenesis of various immune disorders such as fever, septic shock, arthritis and inflammatory reaction." (PMID 11986770, 2002). "We characterized TMJ involvement in three inflammatory arthritis models: collagen-induced arthritis (CIA), K/BxN serum-transfer arthritis (STA), and human TNF-α transgenic mice (hTNFtg)." (PMID 40755771, 2025). "There were no studies investigating MAA in other RA animal models, such as collagen antibody induced arthritis, zymosan-induced arthritis, methylated BSA model, tumor necrosis factor (TNF)-alpha-transgenic mice, K/BxN mice, or SKG mice." (PMID 41368636, 2025). "The in vivo effects of tacrolimus were assessed in an AS mouse model by evaluating clinical arthritis scores and analyzing inflammatory cytokine-producing cells (IFN-γ, IL-17A, and TNF-α) via flow cytometry." (PMID 40757951, 2025). "In the AS mouse model, tacrolimus treatment resulted in significantly lower clinical arthritis scores and reduced production of inflammatory cytokines (IFN-γ, IL-17A, and TNF-α)." (PMID 40757951, 2025). "This is in contrast with our data for mice which showed that neutralizing both TNF and LTα3 with ETA, or neutralizing LTα3 in TNFko/ko mice, was effective in reducing clinical symptoms of arthritis." (PMID 40650132, 2025). "SCFAs correlate with increased Tregs and decreased IL-17A, IL-6, and TNF-α in CIA rats, and their administration alleviates arthritis severity by expanding Foxp3+ IL-10+ Tregs." (PMID 41019075, 2025). "In a first approach to assess the role of LTα3 in the effector phase of arthritis, C57BL/6 mice were treated with antibody specific for LTα3 or with ETA that neutralizes mouse TNF, as well as LTα3." (PMID 40650132, 2025). "For instance, chlorogenic acid has been shown to reduce B-cell activating factor (BAFF) and TNF-α levels, inhibit the apoptosis of MH7A cells, and slow the progression of arthritis in CIA mice." (PMID 40124380, 2025). "WTD significantly decreased the expression of TNF-α, IL-1β, monocyte chemoattractant protein-1 (MCP-1), and MMP-3 in the synovium, mitigating arthritis." (PMID 41019075, 2025). "Anti-TNF therapies have demonstrated reasonable response rates for treating cutaneous manifestations, arthritis, and ocular EIMs in IBD, suggesting a role for TNF-dependent mechanisms in EIM pathophysiology." (PMID 40565205, 2025). "For example, TNFR1 forms a trimeric complex upon binding to its natural ligand TNF-α, which attenuates TNF-α-induced NF-κB and p38 MAPK signaling, thereby reducing arthritis severity in mice." (PMID 41249580, 2025). "It was also found that CA improved the symptoms of arthritis in rats with type II CIA and decreased the levels of inflammatory markers, including TNF-α, IL-1β, IL-6, IL-12, and IL-17A." (PMID 39061843, 2024). "For example, Dnase2-/- mice develop a polyarthritis and induce high levels of TNF-α and IL-6 in affected joints, and blockade of TNF-α or IL-6 has a therapeutic effect on arthritis in Dnase2-/- mice." (PMID 39478149, 2024). "In the present study, we showed that in the same model of established adjuvant-induced arthritis, a one-week delay in oral AUR administration resulted in reductions in both TNF-α and IL-17 levels." (PMID 39687160, 2024). "Various drugs, such as NSAIDs, GC, SSZ, MTX, HCQ, and TNF inhibitors, are currently used to treat ICI arthritis." (PMID 39122457, 2024). "EGCG inhibits TNF-α production in inflammatory conditions, particularly in models of IBD and arthritis." (PMID 39597805, 2024).
Arthritis (continued). "TNF-α levels were significantly lower in all doses of AUR and UMB treatments compared to the arthritis control group (p < 0.05)." (PMID 39687160, 2024). "Colchicine is also the initial treatment for BS arthritis, but immunosuppressants like azathioprine (AZA) or anti-tumor necrosis factor alpha (anti-TNFa) should be considered in chronic or refractory cases." (PMID 39359917, 2024). "Prior studies show that during arthritis, Cyclooxygenase-2 (COX-2), Tumor Necrosis Factor-α (TNF-α), inducible Nitric Oxide Synthase (iNOS), and 18 S ribosomal RNA play key roles in promoting inflammation by inducing the NF-κβ pathway." (PMID 38724967, 2024). "Previous work has shown that quercetin significantly reduces TNF-α production in CIA rats and protects mice from arthritis." (PMID 39390367, 2024). "Salubrinal, a selective eIF2α dephosphorylation inhibitor, has been shown to reduce the release of pro-inflammatory cytokines (IL-1β, IL-2, IL-13, and TNF) and the expression of the Dusp2 gene in a mouse model of CIA, alleviating arthritis progression." (PMID 39076977, 2024). "MOIG treatment inhibited the production of IL-1β, IL-6, IL-8 and TNF-α, and reduced the matrix degradation enzymes expressions of MMP2 and MMP3 in TNF-α-stimulated FLSs, thereby blocking the spread of arthritis to distant joints." (PMID 39444614, 2024). "In our present study, indomethacin reduced pain behavior, paw volume, arthritic score, TNF‐α level, and oxidative stress markers in CFA‐induced arthritis rats." (PMID 39479654, 2024). "Flavonoids from Litsea coreana were found to inhibit IRE1/mTORC1/TNF-α-regulated inflammatory responses triggered in peritoneal macrophages of CIA mice and ameliorated arthritis in a dose-dependent manner in CIA mice." (PMID 39076977, 2024). "Catechins can reduce secondary inflammation in rats by inhibiting the production of IL-1, TNF-α, and PGE2 in an adjuvant-induced arthritis model and by upregulating the expression of EP2 in rat synovial cells." (PMID 38999143, 2024). "An anti-TNF-α TFO in a 0.9% NaCl aqueous solution was injected into acute- and chronic-arthritis model rats, and significant decreases were observed in the disease development in both models." (PMID 37896275, 2023). "The findings showed that TNF- and COX2 serum levels were raised in arthritis induced group by 2-fold and 1.9-fold, respectively, in comparison to the norm values." (PMID 36757520, 2023). "Triptolide, an effective component of TwHF, has been shown to reduce the levels of TNF-α, CXCL2, and VEGF in arthritis model." (PMID 38013265, 2023). "The administration of PeaNoc XL as an adjunct to standard therapy resulted in a significant reduction in levels of TNF-α (P<0.01), IL-1β (P<0.001), IL-6 (P<0.01), and CRP (P<0.01) in arthritis patients experiencing joint pain and inflammation." (PMID 37767025, 2023). "Cinnamaldehyde can not only significantly reduce the IL-6 content of inflammatory mediator TNF-α in peripheral mononuclear cells of RA patients, but also inhibit the release of IL-1β and matrix MMP-13 from synovial fibroblasts in arthritis patients." (PMID 37033930, 2023). "As a result of blood inflammatory cytokine analysis using an ELISA kit, it was confirmed that the expression levels of TNF-α, IL-6, PGE2, MMP-2, and NO were significantly increased in the serum of mice with arthritis induced by MIA." (PMID 37623223, 2023). "Consistent with the decreases in arthritis score by TAS5315, TAS5315 markedly decreased the levels of TNF-α, IL-1β, and IL-6." (PMID 36821545, 2023). "Using Simoa technology, we measured TNF-α concentrations between 3 and 26 pg/mL (median = 10.8 pg/mL) in synovial fluid (SF) from eighteen JIA patients’ knees with active arthritis." (PMID 37822935, 2023). "During this process an axis between TNF and SOX4 protein has been suggested, where SOX4 works as pivotal mediator and target of these cytokines to enable arthritis progression." (PMID 36835620, 2023).
Arthritis (continued). "TNF-α, IL-6, and IL-1 β production were all tempered expressively in CFA-induced arthritis rats given fustin in our study." (PMID 37520245, 2023). "Animal studies have shown that ethanolic extract of pomegranate peel can significantly increase paw withdrawal latency and reduce adverse histological changes and arthritis scores, and reduce serum RF, MDA, IL-1β and TNFα." (PMID 37033930, 2023). "At the molecular level, CC plays a critical role in the treatment of arthritis by regulating NF-κB, Wnt1/β-catenin and PI3K/AKT/mTOR signaling pathway, inhibiting the expression of IL-6, IL-1β, MMP-3 and TNF-α." (PMID 37637408, 2023). "Through direct and indirect binding to SOX4 TF, several upstream factors and signaling molecules have been recently reported to target SOX4 during arthritis, such as ROS)/TGF, TNF, SMOC2, AGEs, Lnc PART1, and the miRNA, miR-31." (PMID 36835620, 2023). "We demonstrated the utility of monitoring running in the TNF-Tg mouse model of RA through remarkable changes in running outcomes for TNF-Tg vs WT mice and the effects of exercise on ILD and inflammatory-arthritis severity." (PMID 36732826, 2023). "RANKL secretion by FLSs is stimulated by IL-1, IL-6, and TNFα produced by macrophages, creating the macrophage–FLS–osteoclast axis for the RANKL-stimulated osteoclastogenesis in arthritis." (PMID 37569682, 2023). "In contrast, the microbiota is dispensable for TNF‐driven musculoskeletal pathology in TNFemARE/ARE mice, as GF TNFemARE/ARE mice still develop severe arthritis." (PMID 37694693, 2023). "ELISA detection showed that three doses of WFR can alleviate arthritis in CIA rats in a dose-dependent manner by downregulating abnormally elevated levels of IL-1β, IL-6, and TNF-α (p < 0.01)." (PMID 38098062, 2023). "TNF-α upregulation is present in IBD, arthritis and CNO, explaining the positive response to anti-TNF-α." (PMID 38137947, 2023). "In vivo, compound 2 ameliorated arthritis symptoms and reduced serum levels of TNF-α and NO and synovial expressions of p-Akt and p-ERK in the CFA-induced arthritis rat model." (PMID 37511889, 2023). "They found that injection of MTX into MRL/lpr mice, a model for systemic autoimmunity including arthritis, at ZT18 decreased the serum levels of IgG-rheumatoid factor, TNFα, and serum amyloid A (SAA, a marker for acute inflammation) than the ZT6 injection." (PMID 37569682, 2023). "Monoclonal bispecific antibodies against TNF-α and CXCL10 attenuated arthritis symptoms in mice by inhibiting CXCL10-mediated CD8+ T cell migration." (PMID 36860872, 2023). "Cedrol reduced the paw's thickness by inhibiting the release of inflammatory mediators (IL-1B and TNF-α), indicating its anti-inflammatory potential in CFA-induced arthritis." (PMID 35509836, 2022). "In collagen II-induced arthritis male DBA/1J mice, ginkgolide B (10, 20, and 40 μM, i.p., for 43 days) decreased the serum levels of IL-1β, IL-6, TNF-α, MMP-3, and MMP-13 and increased the anti-inflammatory cytokine IL-10." (PMID 35368757, 2022). "In vivo Study DBA/1 mice (n = 28) were immunized with bovine type II collagen to induce arthritis and subsequently treated with OPG-Fc or anti-TNFα antibody or both." (PMID 36059831, 2022). "Andrographolide treated CFA-induced arthritis by inhibiting the expression of a series of arthritis-related molecules, including COX-2, NF-κB, p-p38, CD40, TNF-α, IL-1β, and IL-6." (PMID 36238575, 2022). "When treating complete Freund’s adjuvant-induced arthritis, AG inhibits a series of molecules related to arthritis, such as cyclooxygenase-2 (COX-2), NF-κB, p-p38, CD40, TNF-α, IL-1β, and IL-6." (PMID 36188549, 2022). "Pro-inflammatory markers TNF-α, NF-κB, IL-6, IL-1β, and COX-2 were significantly downregulated with piroxicam, EEJR, and NHJR in comparison with the arthritis group." (PMID 35422870, 2022).
Arthritis (continued). "We detected systemic production of TNF-α and IL-6 in the sera of 6-wk-old DNase II−/−Ifnar1−/− and DNase II−/−STINGS365A/S365A mice before the development of arthritis." (PMID 34901991, 2022). "Andrographolide significantly lowered the levels of proinflammatory cytokines (TNF-α, IFN-γ, IL-6, and IL-17A) in the plasma of mice with complete Freund’s adjuvant (CFA)-induced arthritis while improving the levels of the anti-inflammatory cytokine IL-10." (PMID 36238575, 2022). "Most notably, a recent study showed that anti-tumor necrosis factor (TNF)-α treatment significantly decreased lipid peroxidation, indicating that it is a crucial event in arthritis." (PMID 35740050, 2022). "In a supplemental study, DTHA-mice were euthanized throughout 14 days after induction of arthritis, and blood was analysed for important markers and mediators of RA (SAP, TNF-α and IL-6)." (PMID 35077491, 2022). "Arthritis induction led to high levels of IL-1β, CXCL1 (chemokine (C–X–C motif) ligand 1), IL-6, TNF-α, and VEGF, which were markedly decreased after BPI treatment three-, two-, two-, 15-, and threefold, respectively." (PMID 36361854, 2022). "We successfully established a humanized mouse model of ICI-related severe arthritis and pneumonitis with a higher frequency of TNF-α+ T cells, which were significantly mitigated by anti-TNF-α treatment." (PMID 36016934, 2022). "Phlomisoside F (5, 10, and 20 mg/kg, p.o., for 28 days) inhibited the expression of TNF-α, IL-1β, IL-6, COX-2, and 5-lipoxygenase (5-LOX), and increased the expression of IL-10 in complete Freund's adjuvant-induced arthritis male Wistar rats." (PMID 35368757, 2022). "The low-dose ferroptosis inducer, IKE, when combined with the anti-TNF antagonist etanercept, was able to trigger fibroblast ferroptosis and lead to reduced cartilage and bone damage in the CIA experimental arthritis model." (PMID 35115492, 2022). "In addition, since anti-TNF therapy affects both the lymphatic system and the joint simultaneously, the ability to evaluate the direct relationship between lymphatic contractility and arthritis may be a limitation of this study." (PMID 35882971, 2022). "It was previously found that tetrandrine inhibited TNF-α and IL-1β in FCA-induced arthritis at a concentration of 20 mg/kg." (PMID 35222675, 2022). "Finally, local administration of uridine in the joint could prevent the development of antigen-induced arthritis, probably through downregulation of adhesion molecule expression, decreased production of TNF-α and IL-6, and inhibition of leukocyte extravasation." (PMID 36235070, 2022). "In the context of early-stage arthritis, the macrophages in the synovium are stimulated by inflammatory factors such as LPS, IFN-γ, and TNF-α, thus polarizing towards the M1 phenotype." (PMID 36032667, 2022). "Second, etanercept, an agent of anti-inflammatory tumor necrosis factor inhibitors (anti-TNF), normally used to treat certain types of arthritis, was found effective in the treatment of CPSP." (PMID 36035203, 2022). "TNF-α can induce the activation of NF-κB signal transduction pathway in synovial cells, which is closely related to the role of TNF-α in arthritis synovial inflammation and bone destruction." (PMID 36090056, 2022). "Biological agents such as tumor necrosis factor (TNF) inhibitors and interleukin (IL)-6 receptor inhibitors can be utilized when arthritis is uncontrolled or toxic effects arise with DMARDs." (PMID 35571141, 2022). "Collagen-induced arthritis model rats were randomly treated with IL-1β/TNF-α siRNA, BMSCs and IL-1β/TNF-α siRNA + BMSCs for 28 days." (PMID 36288143, 2022). "Inhibition of TNF-α expression and TNF-α antibody therapy can effectively reduce arthritis and synovitis symptoms in RA patients." (PMID 34093213, 2021). "A cationic hydrogel made of c-agarose coupled with AO against tumor necrosis factor alpha (TNF-α) showed high target affinity to the spleen and alleviated inflammation in arthritis animal models." (PMID 34771719, 2021).
Arthritis (continued). "In the murine collagen type II-induced arthritis model, it was found that LBP decreased the expression of inflammatory mediators TNF-α, IL-6 and IL-17 in a dose-dependent manner." (PMID 34404395, 2021). "PNS attenuated arthritis, restored LMC coverage and draining function of mature LVs, inhibited TNF-mediated NO expression, and reduced LMC apoptosis." (PMID 33602317, 2021). "From a pathophysiologic perspective, TNF-driven arthritis, which is a model of myeloid cell-mediated disease, is associated with activation of microglia and neuroinflammation of certain brain regions, a pattern that is not seen in lymphoid cell-based arthritis." (PMID 34830268, 2021). "Results showed that kurarinone treatment reduced arthritis severity of CIA mice, as well as their levels of proinflammatory cytokines, TNF-α, IL-6, IFN-γ, and IL-17A, in the serum and paw tissues." (PMID 33924467, 2021). "Anti-TNF, as one of the benchmarks in the treatment of RA, was also employed to treat AIA rats with advanced arthritis in this study." (PMID 33846342, 2021). "TQ (10 mg/kg body weight) significantly downregulated the elevated level of Toll-like receptor (TLR) and other inflammatory cytokines (TNF-α, IL-1, and IL-6) in a Freund’s complete adjuvant (FCA)-induced arthritis rat in vivo model." (PMID 34067322, 2021). "In a model of arthritis, endothelial dysfunction was only observed in rats with a persisting imbalance between NOS and COX-2 pathways, higher plasma levels of IL-1β and tumor necrosis factor-α (TNF-α)." (PMID 33868242, 2021). "Following the onset of arthritis, the anti‐TNF‐α group received the TNF‐α inhibitor, etanercept, for 6 weeks." (PMID 34713972, 2021). "Animal models including proteoglycan aggrecan-induced arthritis (PGIA), HLA-B27 transgene rats, TNF-α transgenic mice, and DBA/1 mice, have been designed to investigate the pathogenesis of AS43,47–49." (PMID 34764263, 2021). "RA is an inflammatory disease, and the inflammatory markers are highly expressed in synovial fluid and serum of patients with arthritis, such as C-reactive protein (CRP: an acute-phase protein), interleukin-6 (IL-6), and tumor necrosis factor (TNF-α)." (PMID 34136020, 2021). "To investigate if cytokines other than TNF also affect LMC function, we treated cells with IL-6, an important cytokine for arthritis." (PMID 33602317, 2021). "Free CEL and anti-TNF showed relatively low efficacy in decreasing the paw thickness and ankle diameters of AIA rats with advanced arthritis." (PMID 33846342, 2021). "Tumor necrosis factor-alpha (TNF-α) is a cytokine involved in systemic inflammation and is identified to be a good target to treat arthritis." (PMID 34066890, 2021). "Moringa rivae leaf extract is known to down-regulate the TNF- α and COX-2 expressions in the animal model systems; Fenugreek (Trigonella foenum graecum), extracted in ethanol, ameliorates arthritis in experimental animals and decreased TNF-α expression." (PMID 33711984, 2021). "Maximal respiration was significantly higher in resolving arthritis than veRA FLS, and was significantly reduced by TNFα treatment only in resolving arthritis FLS." (PMID 34512657, 2021). "In the TNF-α-stimulated SFs, a significantly lower expression of NLRP3 and TLR4 was observed in the RA group, compared with the other tested forms of arthritis." (PMID 35126351, 2021). "In CIA animal models, intra-articular adiponectin administration attenuates arthritis by downregulating IL-1, MMP-3, and TNF-α expression in inflamed joints." (PMID 34685605, 2021). "For example, in the acute K/BxN serum-induced arthritis model, signalling via TLR4-MyD88, as well as IL-1α and IL-1β activity, play a more crucial role in disease progression and chronicity than TNF itself." (PMID 33924766, 2021). "In arthritis, oncostatin M (OSM), a cytokine present in synovial fluid and joint tissue, synergizes the action of other inflammatory cytokines (e.g., IL-1, TNF-α, IL-17, lipopolysaccharide (LPS))." (PMID 34834636, 2021).